PDZK1 (PDZ domain containing 1)
Description:
A scaffold protein that connects plasma membrane proteins and regulatory components, regulating their surface expression in epithelial cells apical domains. May be involved in the coordination of a diverse range of regulatory processes for ion transport and second messenger cascades. In complex with NHERF1, may cluster proteins that are functionally dependent in a mutual fashion and modulate the trafficking and the activity of the associated membrane proteins. May play a role in the cellular mechanisms associated with multidrug resistance through its interaction with ABCC2 and PDZK1IP1. May potentiate the CFTR chloride channel activity. Required for normal cell-surface expression of SCARB1. Plays a role in maintaining normal plasma cholesterol levels via its effects on SCARB1. Plays a role in the normal localization and function of the chloride-anion exchanger SLC26A6 to the plasma membrane in the brush border of the proximal tubule of the kidney. May be involved in the regulation of proximal tubular Na(+)-dependent inorganic phosphate cotransport therefore playing an important role in tubule function (By similarity).
Synonyms: NHERF-3; NaPi-Cap1; CAP70; NHERF3; PDZD1; CLAMP
Tractability: Antibody: its Gene Ontology location is reachable by antibodies, with high confidence; UniProt places it where antibodies can reach, with medium confidence. PROTAC: its protein half-life has been measured.
Gene: Protein-coding gene on chromosome 1 (145,670,848 to 145,708,148, reverse strand). Ensembl gene ENSG00000174827.
Subcellular location: Membrane; Cell membrane
Subcellular location (Human Protein Atlas): Nucleoplasm; Vesicles; Cytosol
Gene Ontology:
Molecular function: identical protein binding; PDZ domain binding; protein binding; transporter activator activity; protein-membrane adaptor activity; signaling receptor binding; protein-containing complex binding; scavenger receptor binding
Biological process: carnitine transmembrane transport; positive regulation of protein localization to membrane; positive regulation of protein targeting to membrane; protein localization to plasma membrane; regulation of monoatomic anion transport; xenobiotic detoxification by transmembrane export across the plasma membrane
Cellular component: brush border; extracellular exosome; plasma membrane; apical plasma membrane; brush border membrane; apical part of cell; membrane; microvillus membrane
Genetic constraint (gnomAD): Loss-of-function variants: 19 observed, 20.03 expected, observed/expected ratio (o/e) 0.95, 90% interval 0.66 to 1.39. The synonymous counts are far from expectation, so gnomAD's model fits this gene poorly and the ratio says little. Missense variants: 206 observed, 284.21 expected, observed/expected ratio (o/e) 0.72, 90% interval 0.65 to 0.81. Synonymous variants: 67 observed, 104.17 expected, observed/expected ratio (o/e) 0.64, 90% interval 0.53 to 0.79.
Homologues: Orthologues: chimpanzee PDZK1 (99% identical), macaque PDZK1 (97% identical), pig PDZK1 (89% identical), guinea pig PDZK1 (83% identical), rat Pdzk1 (79% identical), mouse Pdzk1 (78% identical), tropical clawed frog pdzk1 (47% identical), zebrafish pdzk1 (45% identical), Caenorhabditis elegans nrfl-1 (19% identical). Paralogues in human: NHERF4 (29% identical), NHERF1 (22% identical), NHERF2 (20% identical).
Diseases named in the same sentence as PDZK1 in open-access papers:
PDZK1 is named in the same sentence as 53 diseases in open-access papers, as found by Europe PMC text mining. Sharing a sentence is not in itself a finding about the gene and the disease. The quoted sentences say what the papers report.
breast carcinoma (17 papers, 2005 to 2024). "The direct molecular interaction between IGF-1R and PDZK1 enhances expression of ER-α associated with breast cancer metastasis." (PMID 29787591, 2018). "Subsequent to the reduction in IGF-1R expression levels resulted in reduce expressions of ER-α and PDZK1, associated with decreased risk of developing breast cancer metastasis." (PMID 29787591, 2018). "A 3-marker signature comprised of high PBK, high ANLN and low PDZK1 expression was associated with decreased recurrence-free survival (p < 0.001) and breast cancer-specific survival (BCSS) (p < 0.001)." (PMID 23547718, 2013). "In this study, we aimed to determine the effect of PARP inhibition on estrogen-induced growth of breast cancer cells and examine whether the potential effect is linked to PDZK1 and IGF-1R expression." (PMID 26183824, 2015). "In contrast, the PDZK1 expression was upregulated in breast cancer, thyroid cancer and hepatocellular carcinoma." (PMID 39011473, 2024). "From two pairs of matched breast cancer samples, we found that some of the detected CNVs contained some genes that were related to breast cancer, such as PDZK1, XRCC4, Fbxl17, ITGBL1, RORA, BAGE, AMOTL1, RAP80, PIWIL4, CSE1L, and USP18." (PMID 34262604, 2021). "PDZK1 acts as a tumor suppressor in gastric cancer and renal cancer, but in esophageal adenocarcinoma, breast cancer, and multiple myelomas (MMs), the overexpression of PDZK1 promotes cancer development or drug resistance." (PMID 35111672, 2021). "The gene mapping of 24 DEGs through PubMed, OMIM, MeSH, and PMC databases provided eight significant breast cancer associated genes: ID4, NCOA1, RHEB, PDZK1, PLAUR, AKC1R2, ANXA1 and SLIPI." (PMID 33593445, 2021). "Our results suggest that fulvestrant is an effective drug that inhibits the pathogenic/carcinogenic effects of estrogen dependent IGF-1R, IRS-1, ER-α and PDZK1 signaling pathways to control breast cancer progression." (PMID 29787591, 2018). "Fulvestrant should be used to inhibit multiple targets (IGF-1R, IRS-1, PDZK1 and ER-α) involved in breast cancer progression." (PMID 29787591, 2018). "More importantly, our results demonstrate a novel function for PDZK1 and find a molecular crosstalk between biological regulatory growth factors that are involved in breast cancer signaling." (PMID 29787591, 2018). "Among the candidates that can also mediate the growth inhibitory action of the compound, we have further characterized the JQ1-associated downregulation of two important breast cancer oncogenes, BCAS1 and PDZK1." (PMID 28881673, 2017). "PDZK1 promotes estrogen-mediated growth of breast cancer cells, whereas BCAS1 undergoes gene amplification-associated overexpression in breast cancer and has been implicated in breast cancer progression." (PMID 28881673, 2017). "We have recently shown that PDZK1, a scaffold protein, plays an important role in estrogen-induced growth of breast cancer cells and demonstrated a strong correlation between the expression of the protein and human breast malignancy." (PMID 26183824, 2015). "We recently showed that the scaffolding protein PDZK1 is critical for 17β-estradiol (E2)-induced growth of breast cancer cells." (PMID 26183824, 2015). "NHERF‐I, NHERF‐II, and PDZK1 are abundantly expressed in breast cancer or cell lines, where NBCn1 expression is upregulated by 20–30% compared to that in matched normal breast tissue." (PMID 24844638, 2014). "PDZK1 is a known estrogen response gene in breast cancer, with proposed roles in signal transduction, cell polarity and ion exchange gating." (PMID 23547718, 2013). "An in-house statistical re-analysis of the genes assessed by van’t Veer and colleagues in the development the 70-gene prognostic signature identified PDZK1 as a marker of good prognosis in breast cancer, which we confirmed at the protein level in this study." (PMID 23547718, 2013).
breast carcinoma (continued). "For example, PDZK1, which is related to cancer progression, had been reported in different kinds of cancers, such as gastric cancer, renal cell carcinoma, and breast cancer." (PMID 35111672, 2021). "We have shown a strong relationship between PDZK1 and IGF-1R expression in human breast cancer and that PDZK1 may be a determinant in breast tumorigenesis." (PMID 26183824, 2015). "Furthermore, among 150 breast cancer risk regions identified by genome-wide association studies, several ERGs identified in this study (BARX2, CBX6, KCNN4, MYEOV, PDZK1 in 300 ERGs) were included as the targets for cancer drivers, transcription factors, and signaling proteins." (PMID 35976950, 2022). "PDZK1, an oestrogen-responsive gene associated with good prognosis showed differential expression between ER positive and negative tumour cell lines, confirmed by IHC and PDZK1 protein expression was associated with improved breast-cancer-specific survival, ER positivity and low-tumour grade." (PMID 22275966, 2008). "In summary, breast cancer cells exhibits activation of multiple growth promoting factors: IGF-1R, IRS-1, PDZK1 and ER-α." (PMID 29787591, 2018). "The molecular link between PDZK1 and IGF-1R was supported by a significant correlation between protein and mRNA levels of the two factors in two independent cohorts of human breast cancer tissues." (PMID 26183824, 2015). "In addition, Shimizu demonstrated that PDZK1 physically binds with ABCG2 and regulates breast cancer resistance." (PMID 38669103, 2024). "There is a strong correlation of PDZK1 with multiple signaling pathways including estrogen dependent IGF-1R and chemokine (C-X-C motif) receptor 4 (CXCR4) signaling which can be targeted therapeutically to treat breast cancer." (PMID 29787591, 2018). "Antibodies against anillin (ANLN), PDZ-Domain Containing 1 (PDZK1) and PDZ-Binding Kinase (PBK) demonstrated specificity via Western blot analysis and exhibited concordant IHC staining on cell pellet arrays across 7 breast cancer cell lines." (PMID 23547718, 2013). "Finally, three antibodies (PDZK1, ANLN, PBK) were successfully optimised on full-face paraffin embedded sections of breast cancer tissues and subsequently selected for screening on TMAs." (PMID 23547718, 2013). "Recently, a study reported an association between serum levels of estradiol and gene expression of trefoil factor 1 (TFF1), growth regulation by estrogen in breast cancer 1 (GREB1), PDZ domain containing 1 (PDZK1) and progesterone receptor (PGR) in ER+ breast carcinomas." (PMID 21812955, 2011). "Interestingly, expression microarray analyses indicate that, upon JQ1 administration, the antitumoral phenotype also involves downregulation of relevant breast cancer oncogenes such as the Breast Carcinoma-Amplified Sequence 1 (BCAS1) and the PDZ Domain-Containing 1 (PDZK1)." (PMID 28881673, 2017).
gout (14 papers, 2017 to 2025). A condition characterized by painful swelling of the joints, which is caused by deposition of urate crystals. "Common variants near PDZK1, which encodes a urate transport accessory molecule, have been associated with uric acid levels and gout risk." (PMID 40463523, 2025). "The results of a case-control study suggest that PDZK1 genetic polymorphism rs12129861 (C > T) is associated with reduced gout risk in male Han Chinese (OR = 0.727, 95% CI: 0.562; 0.940)." (PMID 33810064, 2021). "In a large population of European ancestry, ABCG2 and PDZK1 gene-sex interactions exist for gout risk, with the serum urate-raising alleles exerting a greater influence on gout risk in men than in women." (PMID 30626429, 2019). "We are the first to report significant sex-specific differences for the PDZK1 variant (rs1471633) on gout risk." (PMID 30626429, 2019). "In this large population of European ancestry, we have identified gene-sex interactions for ABCG2 (rs2231142) and PDZK1 (rs1471633) for gout risk, with the serum urate-associated SNPs exerting a greater influence on gout risk in men than in women." (PMID 30626429, 2019). "The SNPs rs1967017 and rs12129861 of the PDZK1 gene were associated with gout in men of Han Chinese." (PMID 30123371, 2018). "In addition, ABCG2 and PDZK1 gene-gender interactions are associated with gout risk in European populations." (PMID 35922835, 2022). "Studies reporting the association of PDZK1 variants with gout have demonstrated mixed findings." (PMID 30626429, 2019). "Three LD blocks existed in chromosome 1 for the variants relating to gout, which were composed of genes DNAJC16, AGMAT (first block), PDZK1, CD160, NUDT17 (second block), TRIM46, MUC1, MTX1, and ASH1L (third block)." (PMID 36221101, 2022). "The SLC17A1 gene is one of the loci associated with serum urate level and gout and encodes NPT1, which is a Cl-dependent urate transport interacting with NHE-RF3 encoded by the PDZK1 gene." (PMID 31947599, 2020). "In people of European ancestry, gene-sex interactions for gout risk exist for ABCG2 and PDZK1, with the effect alleles exerting a greater influence on gout risk in men than in women." (PMID 30626429, 2019). "After multiple correction, except for the genes PDZK1 and SLC17A4, the remaining ten genes still had effects on the risk of gout with a PFDR value less than 0.05." (PMID 28252667, 2017). "Furthermore, some association analyses have also shown associations between gout and urate transporter genes URAT1, NPT1, OAT4/SLC22A11 and OAT10/SLC22A13, and scaffold protein genes PDZK1 and LRRC16A, which bind to various transporters and form transportosomes with them." (PMID 31975031, 2020). "Interestingly, three genes (PDZK1, GCKR and HNF4G) associated with urate influenced the risk of gout, but the other five genes (TCF7L2, LRRC16A, ESR1, NRXN2 and ALPK1) did not, suggesting that elevated serum urate concentration is necessary but not sufficient for the pathogenesis of gout." (PMID 28252667, 2017). "None of the variants of the known gout and hyperuricemia-related genes were co-segregated with the disease phenotype in this family, including ABCG2, SLC2A9, SLC22A11, SLC22A12, SLC17A1, SLC17A3, PDZK1, and INHBB." (PMID 39433541, 2024).
hyperuricemia (10 papers, 2019 to 2025). An abnormally high level of uric acid. "It contains 4 protein domains; the PDK domain of PDZK1 is mainly involved in regulating the subcellular localization of various uric acid transporters, and some studies have found that its rs12129861 mutation is bound up with hyperuricemia and gout pathogenesis." (PMID 36420358, 2022). "Hyperuricemia response affects the expression of PDZK1; PDZK1 affects the proliferation, migration, and apoptosis through the STAT3/C-myc pathway in hepatocellular carcinoma." (PMID 36420358, 2022). "It indicates that hyperuricemia response affects the expression changes of PDZK1 is more obvious, and then, we choose PDZK1 in the next study." (PMID 36420358, 2022). "UA drives excretion through the activation of signaling cascades involving NLRP3, PI3K/Akt and MAPK, leading to the augmentation of PDZK1 and ABCG2 expression, thereby mitigating the effects of hyperuricemia." (PMID 38094893, 2023). "As PDZK1 is a scaffold protein for many ion-channel transporters and PDZK1 increases the apical localization of ABCG2, a urate transporter in the intestine, increased PDZK1 expression can increase urate absorption and thereby contribute to hyperuricemia." (PMID 33919522, 2021).
hepatocellular carcinoma (9 papers, 2010 to 2024). A malignant tumor that arises from hepatocytes. "Hepatoma cells stably knocked down for PDZK1 expression became less susceptible to HCV infection; this effect on HCV infectivity was related to PDZK1 ability to bind SR-BI." (PMID 24278733, 2012). "These may include phosphorylation of Ser-509 in the C-terminus of PDZK1, which is associated with increased SR-BI abundance in rat hepatoma cell culture and/or association with other proteins in a macromoleular complex." (PMID 20949066, 2010). "Specifically we show that the association between SR-BI and PDZK1 is important for efficient entry of HCV into hepatoma cells and suggest that disruption of this interaction may be a future target of anti-HCV therapy." (PMID 20949066, 2010). "PDZK1 affects proliferation, migration, and apoptosis of hepatocellular carcinoma through the STAT3/C-myc pathway." (PMID 39533594, 2024). "The molecular targets and associated mechanisms of hepatocellular carcinoma (HCC) have been widely studied, but the roles of PDZK1 in HCC are unclear." (PMID 38532426, 2024). "We also studied the effect of the same cytokines on PDZK1 expression in the hepatoma cell line Huh-7, which also express PDZK1." (PMID 28223944, 2017). "Further studies involving the use of polarized hepatoma cells or primary hepatocytes in which PDZK1 expression has been ablated are required to accurately predict the relative importance of PDZK1 to HCV infection in the human liver in vivo." (PMID 20949066, 2010). "Taken together our results indicate that the interaction of PDZK1 with SR-BI contributes to the efficient infection of hepatoma cells by HCVcc." (PMID 20949066, 2010). "First, we confirmed the high expression of the PDZK1 gene in human hepatocellular carcinoma." (PMID 36052278, 2022). "Since the PPARα agonist GW7647 increased PDZK1 expression in Huh-7 hepatoma cells, as well as in Caco-2BBE cells, it is possible that the positive effect of RA on PDZK1 expression exerts its effect via binding of RXRα to the PPRE element as well as the RARE element." (PMID 28223944, 2017). "Here we demonstrate that stable shRNA-knockdown of PDZK1 expression in human hepatoma cells significantly reduces their susceptibility to HCV infection, and that this effect can be reversed by overexpression of full length PDZK1 but not the first PDZ domain of PDZK1 alone." (PMID 20949066, 2010).
gastric cancer (8 papers, 2020 to 2024). A primary or metastatic malignant neoplasm involving the stomach. "Frequent downregulation of PDZK1 expression in gastric cancer specimens is associated with the disease progression and poor prognosis of study subjects with gastric cancer." (PMID 36052278, 2022). "Recently, PDZK1 was reported to play a role in renal cancer and gastric cancer progression by regulating SHP-1 and PTEN phosphorylation, respectively." (PMID 38604999, 2024). "The low-level PDZK1 expression had been reported in renal cell carcinoma and gastric cancer, and exhibited tumor suppressive effects." (PMID 39011473, 2024). "PDZK1/AKT/E-CAD is a downstream signaling pathway of MAP17 and is one of the signaling pathways involved in gastric cancer." (PMID 38586313, 2024). "In conclusion, our study confirmed that exosomal LINC00853 is a potential biomarker of gastric cancer and revealed its regulatory effects on the MAP17/PDZK1/AKT pathway in gastric cancer." (PMID 38586313, 2024). "In vivo and in vitro studies have shown that PDZK1 inhibits PI3K-Akt activation by inhibiting PTEN phosphorylation, thereby inhibiting the proliferation of gastric cancer cells." (PMID 36052278, 2022). "Signalling through the PDZK1/PTEN/PI3K axis resulted in reduced growth and proliferation of gastric cancer (GC) cells." (PMID 33659963, 2020). "Indeed, low PDZK1 correlated with LEF1 hyperactivity, whereas high PDZK1 did not, supporting the idea that PTEN C-tail hyperphosphorylation drives pro-tumorigenic WNT signaling in gastric cancers in which PDZK1 expression is compromised." (PMID 37225693, 2023).